ITIH2 (inter-alpha-trypsin inhibitor heavy chain 2)
Description:
May act as a carrier of hyaluronan in serum or as a binding protein between hyaluronan and other matrix protein, including those on cell surfaces in tissues to regulate the localization, synthesis and degradation of hyaluronan which are essential to cells undergoing biological processes.
Synonyms: ITI-HC2; SHAP; H2P
Tractability: Antibody: UniProt places it where antibodies can reach, with medium confidence; UniProt predicts a signal peptide or a membrane-spanning region; its Gene Ontology location is reachable by antibodies, with medium confidence. PROTAC: its protein half-life has been measured.
Gene: Protein-coding gene on chromosome 10 (7,699,386 to 7,758,675, forward strand). Ensembl gene ENSG00000151655.
Subcellular location: Secreted
Subcellular location (Human Protein Atlas): Golgi apparatus; Predicted to be secreted
Pathways (Reactome):
Metabolism of proteins: Post-translational protein phosphorylation; Regulation of Insulin-like Growth Factor (IGF) transport and uptake by Insulin-like Growth Factor Binding Proteins (IGFBPs)
Gene Ontology:
Molecular function: hyaluronic acid binding; protein binding; endopeptidase inhibitor activity; serine-type endopeptidase inhibitor activity
Biological process: hyaluronan metabolic process
Cellular component: blood microparticle; extracellular exosome; extracellular matrix; endoplasmic reticulum lumen; extracellular region
Genetic constraint (gnomAD): Loss-of-function variants: 70 observed, 70.88 expected, observed/expected ratio (o/e) 0.99, 90% interval 0.81 to 1.21. The upper end of that interval is the gene's LOEUF score, 1.21, which puts it in group 5 of 6, group 1 being the genes least tolerant of losing a copy. Missense variants: 865 observed, 932.36 expected, observed/expected ratio (o/e) 0.93, 90% interval 0.88 to 0.98. Synonymous variants: 338 observed, 359.35 expected, observed/expected ratio (o/e) 0.94, 90% interval 0.86 to 1.03.
Homologues: Orthologues: chimpanzee ITIH2 (99% identical), macaque ITIH2 (97% identical), dog ITIH2 (87% identical), rabbit ITIH2 (86% identical), mouse Itih2 (84% identical), guinea pig ITIH2 (84% identical), rat Itih2 (84% identical), pig ITIH2 (80% identical), tropical clawed frog itih2 (58% identical), zebrafish itih2 (51% identical). Paralogues in human: ITIH3 (38% identical), ITIH1 (36% identical), ITIH4 (32% identical), ITIH5 (31% identical), ITIH6 (30% identical), PARP4 (17% identical), VWA3B (15% identical), VWA3A (14% identical), VWA5A (13% identical), VWA5B1 (12% identical), VWA5B2 (11% identical).
Diseases named in the same sentence as ITIH2 in open-access papers:
ITIH2 is named in the same sentence as 53 diseases in open-access papers, as found by Europe PMC text mining. Sharing a sentence is not in itself a finding about the gene and the disease. The quoted sentences say what the papers report.
breast carcinoma (6 papers, 2008 to 2025). "Loss or downregulation of ITIH2 expression was seen in 70% of breast cancers, 71% of lung cancers, and 70% of renal tumors." (PMID 18226209, 2008). "Despite these results highlighting a limited cellular presence of ITIH2, its role in inflammation and extracellular matrix stabilization suggests potential relevance to breast cancer prognosis." (PMID 40005870, 2025). "The role of ITIH2 in canine mammary neoplasms remains unexplored, representing a promising opportunity to expand knowledge on comparative biomarkers and tumor mechanisms." (PMID 40005870, 2025). "Among the four overabundant proteins identified in the HCF, we highlight inter-alpha-trypsin inhibitor heavy chain H2 (ITIH2) and other members of the ITI family which have been associated with trauma-induced inflammatory responses and breast cancer." (PMID 38256043, 2024). "Previous pan-cancer study on the ITIH family has only explored the expression patterns of ITIHs in 13 cancer types with relatively small sample sizes, and it has been mostly concerned with the expression and clinical significance of ITIH2 in breast cancer." (PMID 33744857, 2021). "To provide further evidence that ITIH2 mRNA is differentially expressed in breast cancer we performed a semiquantitative real-time PCR analysis on a cohort of 36 primary breast carcinomas." (PMID 18226209, 2008). "Next, we analyzed for the first time ITIH2 protein expression in normal breast tissue and breast cancer." (PMID 18226209, 2008). "Investigating ITIH2 expression in human breast cancer we were able to confirm the data obtained by CPA analysis (70% downregulation) by semiquantitative real-time RT-PCR (64% downregulation) in an additional set of breast tumors." (PMID 18226209, 2008). "As the main focus of our workgroups lies on molecular understanding of breast cancer, we chose ITIH2 for a detailed expression analysis in human breast cancer." (PMID 18226209, 2008). "Another major limitation of the previous study was that they have only briefly investigated the prognostic significance of ITIH2 in breast cancer, in which ITIH2 was neither associated with overall survival (OS) nor recurrence-free survival (RFS)." (PMID 33744857, 2021). "For an initial detailed analysis we chose ITIH2 expression in human breast cancer." (PMID 18226209, 2008). "In line with the results derived from the CPA, ITIH2 mRNA downregulation in breast cancer could thus be confirmed by a second independent technique." (PMID 18226209, 2008). "Loss of ITIH2 expression in 70% of cases (n = 50, CPA) could be confirmed by real-time PCR in an additional set of breast cancers (n = 36)." (PMID 18226209, 2008). "This study focuses on two potential biomarkers—Inter-Alpha-Trypsin Inhibitor Heavy Chain 2 (ITIH2) and Enolase 1 (ENO1)—which have been identified in previous research as relevant to canine mammary tumors." (PMID 40005870, 2025). "The prognostic potential of ITIH2 and ENO1 for mammary tumors in bitches was assessed using ROC curve analysis, which revealed limited predictive power." (PMID 40005870, 2025). "Others, such as COL18A1, TGFBI, FGB, ITIH2, ITIH4, and TNC among others, were overrepresented in 3 of 4 signatures and also expressed in mammary carcinoma xenografts." (PMID 37098922, 2023).
colorectal cancer (4 papers, 2022 to 2026). A primary or metastatic malignant neoplasm that affects the colon or rectum. "Overall, underexpression of ITIH2 is associated with longer overall survival of colorectal cancer patients; the overexpression of ITIH2 was associated with poor overall survival." (PMID 40005870, 2025). "Post-translational modification in KNG1, AHSG and downregulation of ITIH2 has been reported in colorectal cancer." (PMID 35109816, 2022). "For instance, elevated expression of ITIH2 in liver hepatocellular carcinoma (LIHC) patients was associated with longer overall survival (OS) (p = 0.019), while increased expression of ITIH2 was associated with shorter OS in colorectal cancer patients that had liver metastases." (PMID 38791985, 2024).
lung carcinoma (4 papers, 2008 to 2025). "In this study, inter-α-trypsin inhibitor heavy chain 2 (ITIH2), an HA-binding protein, was confirmed to be secreted from mesenchymal-like lung cancer cells when cocultured with cancer-associated fibroblasts." (PMID 40178908, 2025). "Using a deep learning–based drug-target interaction algorithm, we identified an ITIH2 inhibitor (sincalide) that inhibited HA matrix formation and migration of lung cancer cells, preventing metastatic colonization of lung cancer cells in mouse models." (PMID 40178908, 2025). "ITIH2 overexpression enhanced the invasive potential of lung cancer cells in mouse orthotopic injection." (PMID 40178908, 2025). "Among the 5 ITIH family members examined, only Itih2 was upregulated in mesenchymal-like lung cancer cells." (PMID 40178908, 2025). "In a previous study, we established that CAFs induce the secretion of ITIH2, an HA-binding protein, by lung cancer cells." (PMID 40178908, 2025). "To elucidate the functional role of ITIH2 in lung cancer cells, we used shRNAs to deplete ITIH2 in murine mesenchymal-like lung cancer cells (344SQ, 344LN, and 531LN2)." (PMID 40178908, 2025). "Down regulation of ITIH proteins and Itih2 in particular has been reported in different types of cancer including breast and lung cancer." (PMID 19812696, 2009). "Furthermore, the effective suppression of lung cancer progression was demonstrated by blocking of HA matrix formation using an ITIH2 inhibitor." (PMID 40178908, 2025). "Sincalide suppresses lung cancer progression by inhibiting ITIH2." (PMID 40178908, 2025). "Furthermore, our findings revealed that ITIH2, in conjunction with the HA matrix, facilitates the motility and invasiveness of lung cancer cells, supporting their pro-invasive role within the lung TME." (PMID 40178908, 2025). "ITIH2 facilitates the migration and metastatic colonization of lung cancer cells." (PMID 40178908, 2025). "The mRNA levels of Itih2 and Zeb1 were markedly higher in mesenchymal-like lung cancer cells than in epithelial-like cells, with a positive correlation observed between their expression levels in all 13 murine lung cancer cell lines." (PMID 40178908, 2025). "An ITIH2 inhibitor (sincalide) prevents lung cancer invasion and progression." (PMID 40178908, 2025). "Similarly, in lung cancers, ITIH2 shows significant downregulation in the altered tissues." (PMID 38203636, 2023). "In human lung cancer cells, ITIH2 and ZEB1 mRNA levels were substantially higher in mesenchymal-like lung cancer cells (H1299) than in epithelial-like cells (HCC827)." (PMID 40178908, 2025). "Overexpression of ZEB1 in epithelial-like 393P cells and HCC827 cells upregulated ITIH2 mRNA expression, while ZEB1 depletion in 344SQ murine lung cancer cells downregulated ITIH2 expression." (PMID 40178908, 2025). "Both ITIH2 and ZEB1 protein levels were elevated in mesenchymal-like lung cancer cells compared with their epithelial-like counterparts." (PMID 40178908, 2025). "Conversely, ectopic expression of ITIH2 in HCC827 and A549 human lung cancer cells enhanced cell migration and invasion." (PMID 40178908, 2025). "Depletion of ITIH2 and HAS2 reduced HA matrix formation and the migration and invasion of lung cancer cells." (PMID 40178908, 2025).
COVID-19 (3 papers, 2021 to 2025). A disease caused by infection with severe acute respiratory syndrome coronavirus 2. "Previously, it was reported that ITIH1 and ITIH2 were more abundant in a COVID-19 survivor group." (PMID 36131342, 2022).
diabetes (3 papers, 2021 to 2023). "ITIH2 is closely related to inflammation, kidney disease, tumors, and diabetes, while FGA is related to chronic inflammation, lipid metabolism, and complications of diabetes." (PMID 37811770, 2023). "Regardless of diabetes and its remission, we found three proteins (KNG1, ITIH2, and APCS) whose abundance changed after 6 months of bariatric surgery when considering all patients as a whole." (PMID 34501327, 2021).
preeclampsia (3 papers, 2022 to 2023). Preeclampsia is a hypertensive disorder of pregnancy that is characterized by new-onset hypertension with proteinuria presenting after 20 weeks of gestation, and depending on mild or severe forms may initially present with severe headache, visual disturbances, and hyperreflexia. "In addition, findings from this study shed light on determining if high Itih2 levels serve as a biomarker for poor outcomes, similar to that described for other disease states (preeclampsia), or mechanistically targeting reducing the inhibitory function of Itih2 to stabilize AoV ECM homeostasis." (PMID 37623368, 2023). "We also report on an ITIH2 protein and APO-related proteins, specific for LOPE that could be explored in the future for personalised management of preeclampsia." (PMID 36351970, 2022). "However, we discovered two novel ITIH protein biomarkers of preeclampsia, which have not been reported previously; ITIH3 and ITIH4 were both increased in EOPE and LOPE whereas ITIH2 was the only one increased in LOPE." (PMID 36351970, 2022).
Sepsis (3 papers, 2024 to 2026). Sepsis is defined as life-threatening organ dysfunction caused by a dysregulated host response to infection. "The decrease in ITIH1, ITIH2 and ITIH4, as compared to the increase in ITIH3, suggest a complex alteration in the protein balance of the IαI-family in sepsis." (PMID 40885913, 2025). "The decreased plasma levels of ITIH1, ITIH2 and ITIH4, as compared to the increased levels of ITIH3, suggest a complex alteration in the protein balance of the IαI-family in the pathophysiology of sepsis." (PMID 40885913, 2025).
breast tumor (2 papers, 2008 to 2025). "The expression of ITIH2 in breast tumors can be explained by its binding with hyaluronic acid, a molecule overexpressed in malignant tumors." (PMID 40005870, 2025). "This widespread distribution complicates the establishment of a direct relationship between ITIH2 and breast tumors, as it is observed in all samples across groups." (PMID 40005870, 2025). "Due to this cut-off, 23 out of 36 breast tumor specimens exhibited ITIH2 downregulation (63.9%) by FC2, whereas 13 out of 36 specimens (36.1%) showed no deregulation or upregulation of ITIH2." (PMID 18226209, 2008).
colon cancer (2 papers, 2021 to 2025). "The top downregulated genes included protease inhibitor Itih2, glycosyltransferase B3gnt5, as well as Eph receptor 6 (Ephb6) and phospholipase Pla2g4c, found to be overexpressed in a colon cancer cell line and human colon cancer tissues." (PMID 40631899, 2025). "As such, ITIH2 might represent the potential core gene for colon cancer liver metastasis." (PMID 34907282, 2021). "Therefore, ITIH2 might represent the potential core gene for colon cancer liver metastasis." (PMID 34907282, 2021). "However, pathological section (Human Protein Atlas) shows that the gene(ITIH2) not detected in tumor cells in colon cancer." (PMID 34907282, 2021).
diabetic retinopathy (2 papers, 2021). "ITIH2 function in metabolic diseases is unclear, although it might play some role as biomarker of diabetic retinopathy." (PMID 34501327, 2021).
glioma (2 papers, 2022). A benign or malignant brain and spinal cord tumor that arises from glial cells (astrocytes, oligodendrocytes, ependymal cells). "Analysis of primary human brain tumors showed significantly higher levels of ITIH2 in normal brain and low-grade tumors compared with high-grade gliomas, indicating an inverse correlation with malignancy." (PMID 35109816, 2022). "Stable overexpression of ITIH2 in U251 glioma cells leads to strong inhibition of cancer cell invasion together with significant inhibition of cell proliferation and promotion of cell-cell adhesion." (PMID 35109816, 2022). "In addition, overexpression of the deregulated ITIH2 protein in glioma cells not only inhibits cancer cell invasion but also suppresses cell proliferation and promotes cell-cell adhesion." (PMID 35898512, 2022).
idiopathic pulmonary fibrosis (2 papers, 2023 to 2025). Idiopathic pulmonary fibrosis (IPF) is a nonneoplastic pulmonary disease that is characterized by the formation of scar tissue within the lungs in the absence of any known cause. "The effects of vitamin D on processes associated with pulmonary fibrosis and cancer were also suggested by changes within the ITIH2 (SHAP) gene." (PMID 38203636, 2023). "In an idiopathic pulmonary fibrosis model, ITIH2 facilitates neovascularization and lung fibrosis, suggesting an analogous role in angiogenesis within the lung TME." (PMID 40178908, 2025). "There have been indications that the ability to regulate angiogenesis may link ITIH2 to the process of pulmonary fibrosis." (PMID 38203636, 2023).
invasive breast carcinoma (2 papers, 2008 to 2024). A carcinoma that infiltrates the breast parenchyma. "Next we studied ITIH2 expression on the protein level by analyzing a comprehensive tissue micro array including 185 invasive breast cancer specimens." (PMID 18226209, 2008). "In 44% (81/185) of invasive carcinomas of the breast, ITIH2 expression was strongly reduced or completely lost while 56% of invasive carcinomas (104/185) maintained moderate to strong ITIH2 expression." (PMID 18226209, 2008). "However, in 44% of invasive breast carcinomas, ITIH2 expression was strongly reduced or completely lost, whereas 56% of invasive carcinomas maintained moderate to strong ITIH2 expression." (PMID 39061201, 2024).
lung adenocarcinoma (2 papers, 2021 to 2025). A carcinoma that arises from the lung and is characterized by the presence of malignant glandular epithelial cells. "Additionally, analysis of The Cancer Genome Atlas (TCGA) data for lung adenocarcinoma (LUAD) revealed a positive correlation between ITIH2 and ZEB1 mRNA levels." (PMID 40178908, 2025).
Alzheimer disease (1 paper, 2022). A progressive, neurodegenerative disease characterized by loss of function and death of nerve cells in several areas of the brain leading to loss of cognitive function such as memory and language. "In addition, synonymous variants in 4 genes [(Cadherin Related 23 (CDH23), SLC9A3 Regulator 1 (SLC9A3R1), Rhomboid Domain Containing 2 (RHBDD2), and Inter-Alpha-Trypsin Inhibitor Heavy Chain 2 (ITIH2)] linked with alzheimer's disease warrant comprehensive scrutiny of genetic variations." (PMID 36434531, 2022).
Arthritis (1 paper, 2023). Inflammation of a joint. "Roles for Itih1 and Itih2 have not been reported in the valve, but in arthritis, pathological degradation of cartilage has been attributed to ITI-HA complexes serving as substrates for ECM proteases—including ADAMTS-5, which has been described as a key player in myxomatous valve disease." (PMID 37623368, 2023).
atherosclerosis (1 paper, 2018). A disease characterized by the build-up of fatty material and calcium deposition in the arterial wall resulting in partial or complete occlusion of the arterial lumen. "Although there is evidence for a protective role of Timp3 in atherosclerosis, Itih1 and Itih2 have not yet been associated with plaque development." (PMID 29208753, 2018).
babesiosis (1 paper, 2023). Babesiosis refers to a condition caused by microscopic parasites that infect the red blood cells. "Other identified proteins that differentiated uncomplicated from complicated babesiosis were various complement cascade components (CFI, CFP, C2, SERPING1, C8G), extracellular matrix components (TGFBI), acute phase proteins (ORM1, ITIH2, ITIH4, FGA, TF, RBP4) and lipoproteins (apoE)." (PMID 37353646, 2023).
cholangiocarcinoma (1 paper, 2025). A carcinoma that arises from the intrahepatic biliary tree (intrahepatic cholangiocarcinoma) or from the junction, or adjacent to the junction, of the right and left hepatic ducts (hilar cholangiocarcinoma). "Itih2 was involved in the acute inflammatory response, providing candidate targets for liver hepatocellular carcinoma and cholangiocarcinoma." (PMID 40906132, 2025).
ductal carcinoma in situ (1 paper, 2024). "According to Hamm (2008), ITIH2 expression was clearly detectable in normal breast epithelium, in hyperplastic gland epithelium, and in ductal carcinoma in situ." (PMID 39061201, 2024).
endometrial cancer (1 paper, 2024). Primary or metastatic malignant neoplasm involving the endometrium (mucous membrane that lines the endometrial cavity). "Six of them were upregulated in endometrial cancer patients (CLU, SERPINC1, ITIH4, C1RL, APOC3 and DSC1), while ten were downregulated (APCS, C9, APOA1, ALB, APOA4, CFHR1, ITIH2, and ACTB)." (PMID 39194522, 2024). "Several blood-based protein biomarker candidates for endometrial cancer detection were suggested, including the Apolipoprotein family (APOA1/4, APOC1/2/3, and APOE), Clusterin (CLU), Inter-alpha-trypsin inhibitor heavy chain (ITIH2 and ITIH4), and Antithrombin III (ATR/SERPINC1)." (PMID 39194522, 2024).